IL10 (interleukin 10)
Diseases named in the same sentence as IL10 in open-access papers (continued):
Sharing a sentence is not in itself a finding about the gene and the disease.
tumor (continued). "AP in cancer, sustaining immunosuppressive cell types and thus the release of cytokines and immune modulatory factors, such as VEGF, IL6, IL10, and TGFβ, and activating survival pathways, inhibits immunosurveillance and enhances tumor survival, metastasis and therapy resistance." (PMID 34830817, 2021). "As the recommended adjuvant treatment for NSCLC patients is cisplatin or carboplatin, it may increase M2 macrophages induced by IL10 secreted from tumor cells." (PMID 34544437, 2021). "Direct stimulation of NK cells by IL-10 would contribute to its anti-tumor effects, while IL-10 could also indirectly mediate NK cell activation via inhibition of ROS secretion by TAMs." (PMID 34497832, 2021). "Indeed, Ezh2-deficient tumor infiltrating Treg cells showed an increased production of the pro-inflammatory cytokines TNF-α, IFN-γ, and IL-2 and a reduced expression of IL-10." (PMID 34262562, 2021). "IL-10, a well-established suppressor of immunity, reduces the antigen presentation capacity of macrophages and inhibits the production of several cytokines that have important roles in tumor immuno-surveillance." (PMID 34034721, 2021). "However, PDAC cells and the TME rather promote differentiation of TH2 cells which are regarded as immune-suppressing and thereby tumor-promoting, mainly because of the release of cytokines like IL-4, IL-5, IL-6, IL-10 and IL-13." (PMID 34638420, 2021). "IL-10 in the TME is derived from several components including tumor cells." (PMID 34806028, 2021). "Likewise, TAM-secreted anti-inflammatory cytokines including TGF-β and IL-10 drive Treg cell expansion to release VEGF-A for sustaining tumor vessel growth." (PMID 34359588, 2021). "In addition, IL-10 didn’t show direct influence on tumor cell viability or Ad-hTERT mediated tumor cell lysis in vitro." (PMID 33717103, 2021). "On the other hand, the high level of IL‐10 delivery by HT‐29‐EXO‐loaded DC might open a path towards immunosuppressive pathway stimulation by tumour cell exosomes, which could provide another explanation." (PMID 33634564, 2021). "IL-10 had significant effects on both tumor volume shrinkage and survival rate." (PMID 33912464, 2021). "Flow cytometry analysis also showed that Treg cells increasingly acquired an anergic phenotype with increasing tumor volume, as measured by an increased number of cells expressing the transcription factor Helios and the key immunosuppressive cytokine IL-10." (PMID 33976133, 2021). "On the other hand, BCG also releases regulatory cytokine such as IL-10 allowing a counterbalance of the inflammatory response favoring the tumor control without so much damage caused by an exacerbated immune response." (PMID 34341449, 2021). "Furthermore, exHSP70 was reported to inhibit the conversion of monocytes to a pro-tumor phenotype, which is potentially due to a diminished expression of pro-tumor cytokines, such as IL-10 and MCP-1." (PMID 34572948, 2021). "In my study, I report that IL-10 has a significant effect on tumor shrinkage and survival in mice." (PMID 33912464, 2021). "Moreover, IL-10-producing monocytes/MDSCs subvert anti-tumour immunity by inhibiting macrophage-derived IL-12 and T cell proliferation in carcinoma models." (PMID 33401460, 2021). "However, peptides identified that stimulate predominantly a regulatory IL-10 response such as citCp450 fail to mediate tumour therapy." (PMID 34858415, 2021). "Along the same line, key immune modulators, such as interleukin-10 (IL-10) or IL-4, are essential for tissue homeostasis but may also dampen anti-tumor immunity." (PMID 34129840, 2021). "Diverse studies have demonstrated that upregulation of B7-H3 expression is associated with impaired T-cell stimulation, suppressed NK-mediated cell lysis, increased IL-10 secretion, and modulation of the Jak/Stat pathway, which contributes to tumor immune suppression and evasion." (PMID 34289871, 2021).
tumor (continued). "Since it was previously demonstrated that the immune suppressive cytokine IL-10 expressed by vaccinia virus prolonged viral persistence 38, and it is known that IL-23 can up-regulate IL-10 expression 39, we measured IL-10 mRNA levels in tumor nodules." (PMID 34093846, 2021). "Moreover, in B-ALL CCR7 ligands potentiate secretion of immunosuppressive IL-10 by tumor cells leading to impaired specific anti-tumor CTL responses." (PMID 34778050, 2021). "Identification of the specific cellular sources of IL-10 that inhibit tumor immunity and targeted suppression of IL-10 production in those cells, or inhibition of IL-10RA signaling in tumor cells, may offer improved safety and efficacy." (PMID 34489941, 2021). "In cancer, IL-10 can control tumor growth by potentiating the effects of anti-tumor CD8 T cells." (PMID 33572870, 2021). "To examine whether TAMs promote tumor migration through the Il-10/Il-10R pathway, we examined tumor cell migration using the transwell assay." (PMID 34711804, 2021). "Moreover, the acquisition of an M2-like phenotype is also caused by the secretion of tumor-derived cytokines such as IL4, IL10, and IL13." (PMID 33562694, 2021). "IL-10 signaling in the tumor infiltrating CD8 T cells is also able to inhibit tumor growth." (PMID 33628584, 2021). "In addition, IL-10 enables tumor cells to evade host immune-system defenses, and promotes their metastasis." (PMID 34513705, 2021). "Reduced CXCL12 levels in an orthotopic tumor model using the murine ovarian cancer cell line ID8-T changed the composition of the immune cell population within tumors, reducing myeloid cells, plasmacytoid dendritic cells and Tregs, while increasing IFN-γ+/IL10+ tumor-infiltrating T lymphocytes." (PMID 33530455, 2021). "Furthermore, expression of Foxp3 and IL-10 was reduced in CD4+CD25+ gated cells isolated from tumor bearing mice treated with TAK-242 in comparison to vehicle-treated controls." (PMID 34771569, 2021). "On the other hand, Tregs might support B-cell tumour growth by efficiently inhibiting anti-tumour responses and by locally secreting IL-10 with pro-survival activity for the malignant B cells." (PMID 34572910, 2021). "Taken together, both IL-10 and Ad-hTERT could induce specific tumor-resident CD8+ T cells responses, and the combination therapy showed stronger effects." (PMID 33717103, 2021). "Moreover, lower T lymphocyte infiltration in HCC was previously reported to associate with innate immunosuppression and tumor mutation burdens, such as Tregs, cytokines (TGF-β and IL-10), and marker gene mutation frequency." (PMID 34745960, 2021). "We observed that FUCA2 was significantly correlated with TGFB1 and IL-10 expression in most tumor types including, which may indicate the potential mechanism of FUCA2 influencing infiltration of TAMs." (PMID 34745134, 2021). "Thus, although IL-10 is known as an anti-inflammatory, immunosuppressive cytokine, it has also been shown to have immunostimulatory activities that inhibit tumor cell growth." (PMID 33809496, 2021). "VEGF, IL-6 and IL-10, which are usually overexpressed in TME, can activate STAT3 signaling, thereby inducing an immature tolerance phenotype in tumor-associated DCs and promoting tumor progression." (PMID 33935714, 2021). "It has been reported that high levels of IL-10 in tumors inhibit tumor metastasis; tumor cell lines transfected with IL-10 show inhibition of cell growth by increasing IFNγ from CD8+ T cells, and IL-10 transgenic mice stimulate CD8+ T cells and limit the growth of immunogenic tumor cells in vivo." (PMID 33809496, 2021). "IL-10 treatment groups had the longest survival and the smallest tumor volume." (PMID 33912464, 2021). "Treg cells may also regulate the anti-tumor effects of T cells via the secretion of important immune suppressive cytokines such as IL-10, IL-35 and TGF-β." (PMID 34012451, 2021).
tumor (continued). "Moreover, the in vivo synergistic anticancer efficacy was evaluated in NCNLCs in xenograft tumor mice models and results showed that NCNLCs upregulated the IL-10 and IL-6 expression in the serum of tumor-bearing mice and inhibited tumor growth." (PMID 33854437, 2021). "Moreover, expression of GATA3, IL-10, and IL-10R was also increased, indicative of a generally immunosuppressive tumor microenvironment in BCG failure." (PMID 33672843, 2021). "The induction of tolerance to tumor advantages may be due to the production of immunosuppressive cytokines, such as IL-10." (PMID 34685762, 2021). "Our reported increases in IL-6 and IL-10 post-IGA are similar to previous reports in several tumour types and similarly the most marked changes were seen following CRYO in this earlier study although this was based on only 4 patients treated with CRYO compared with 31 treated with RFA or MWA." (PMID 34885149, 2021). "Furthermore, a clinical study reported that high IL-10 expression in TAMs plays a significant role in the tumor progression, invasion, metastasis, and poor prognosis of NSCLC." (PMID 34439281, 2021). "Although the functional significance of the positive correlation between the CD8+ cells and Il10 expression in 4NQO-induced tumorigenesis remains to be determined, IL-10 has been shown to participate in intratumoral tumor-specific cytotoxic CD8+ T cell infiltration and activation." (PMID 33921389, 2021). "B cells may negatively regulate tumor immunity and promote tumor progression via IL-10 and TGF-β expression." (PMID 33937018, 2021). "Importantly, a recent work has showed that inhibition of IL-10 boosts ICB-related anti-tumor responses in CLL." (PMID 33917094, 2021). "We checked the level of IL10 in the tumor and hepatic tissues surrounding the tumors." (PMID 33633112, 2021). "NK cells are also involved in the tumor-suppressing effect of IL-10." (PMID 33578830, 2021). "TIGIT can interact with poliovirus receptor (PVR, CD155) on DCs to induce IL-10 secretion for suppressing the Th1 T-cell response, inhibiting the NF-κB pathway and preventing the effective cytotoxic immune response, which is required to reject the tumour." (PMID 34445385, 2021). "IL-10 promotes conversion of M1 macrophages (classically activated, with phagocytosis as a main function) to M2 macrophages (alternatively activated macrophages, TAMs, which facilitate tumor cell evasion from the immune system)." (PMID 34443443, 2021). "As IL-10 has a short half-life and its effectiveness is constrained by distance, it could be found in higher concentration in tumor microenvironment or inflammation site than in the serum." (PMID 33708210, 2021). "Furthermore, experiments using co-cultured tumor cells and macrophages showed augmented expression levels of IL10, IL12, IL6, TNF, CCL5, CCL22, and CSF1 in macrophages, which facilitated M2-like polarization." (PMID 34207286, 2021). "For example, IL-10 enhances the anti-tumor activity of cytotoxic T cells both in vitro and in vivo." (PMID 33708210, 2021). "It is well accepted now that IL-10 is a potent immunosuppressive cytokine that promotes escape of tumor cells from immunosurveillance mediated by antigen-presenting cells and T-helper cells, and, as a consequence, decreases the cytotoxic function of NK cells mainly in a secondary manner." (PMID 34439744, 2021). "Regulation of extravasation by endoglin may also account for lower IL-6 and IL-10 expression and M2 macrophage infiltration seven days after tumor implantation in tumors from Eng-iKOe mice." (PMID 33800564, 2021). "Besides, IL10 together with VEGF inhibits T cell migration to the tumor parenchyma by upregulating the expression of Fas ligands in endothelial cells." (PMID 34566988, 2021). "The anti-inflammatory cytokine interleukin 10 (IL-10) is produced by several cell types, such as monocytes, macrophages, activated T and B cells, eosinophils, mast cells, dendritic cells, epithelial cells and also tumor cells." (PMID 34707513, 2021).
tumor (continued). "M2-like macrophages can produce cytokines including TGF-β and IL-10 to promote tumor growth." (PMID 34194433, 2021). "Th2 cytokines such as IL-4, IL-10, IL-5, IL-9, and IL-6 can down-regulate tumor-specific immunity." (PMID 34222249, 2021). "Therefore, in response to a rapidly adapting cytokine milieu within developing lesions including TGF, IL‐10, IL‐4 and M‐CSF, macrophages acquire a tumour‐promoting, immune‐suppressive phenotype, remodelling the microenvironment in the process." (PMID 32741067, 2021). "Additionally, IL-10, produced in substantial amounts by myeloid-derived suppressor cells (MDSCs), plays a role in creating a tumor-permissive tumor microenvironment." (PMID 34503128, 2021). "The declined expression of tumor growth-promoting IL-10, TGF-β, and VEGF could depend on the altered expression of their upstream regulators: HIF-1α and Hsp70." (PMID 33716751, 2021). "Under the influence of tumor-derived cytokine and growth factors [e.g., VEGF, granulocyte macrophage colony stimulating factor (GM-CSF), macrophage colony-stimulating factor (M-CSF), TGF-β, IL-4, IL-6, and IL-10], MDSCs acquire inhibitory activity against various anti-tumor immune cells." (PMID 34988072, 2021). "Tumor-associated macrophages (TAMs), which contribute to local tumor growth, often express some angiogenesis-promoting factors (e.g., EGFR ligands and VEGF) and immune-suppressing factors (e.g., TGF-β and IL-10), contributing to tumor growth and metastasis." (PMID 34497832, 2021). "The proliferation and metastasis of tumor cells can be promoted by M2 macrophages by releasing anti-inflammatory factors such as IL-10 and TGF-β, immunosuppressive factors such as PGE2, arginase-I, somatomedins such as EGF, CCL18, and HIF-1α and pro-metastasis factors such as MMPs, uPA, and uPAR." (PMID 34506209, 2021). "However, the restriction of inflammatory and immune responses by IL-10 can also favor the development and/or persistence of chronic infections or neoplasms." (PMID 33465107, 2021). "Additionally, tumor-derived exosome-mediated release of IL-10 will activate JAK/STAT-3 pathway and stabilizes FoxP3 expression and differentiation of pTregs." (PMID 33532902, 2021). "We found that single administration of recombinant IL10, CXCL1 or CCL4 attenuates the proliferation of PC cells, and simultaneously induces pro-apoptotic effects, while the stimulation of these cells with a combination of CXCL1/IL10/CCL4 synergistically increased the observed anti-tumour effects." (PMID 34359731, 2021). "Consistent with previous studies, concomitant analyses of immune activation cytokines indicated that nivolumab treatment also significantly increased the production of IFN-γ, IL-2, and TNF-α, of which IFN-γ has been a key cytokine in IL-10 mediated anti-tumor responses." (PMID 34769278, 2021). "An additional T-cell subtype found in the environment of the tumour are regulatory T-cells (Tregs), which suppress the immune response by secreting anti-inflammatory cytokines such as IL-10 or TGFβ, and are characterized by constitutive expression of the transcription factor FoxP3." (PMID 34445385, 2021). "A higher IL-10 concentration resulted in a higher degree of tumor cell suppression." (PMID 33912464, 2021). "Alongside, preclinical data in mouse models, and data of a phase 1 basket trial (NCT02009449) using pegylated IL-10 for treatment of solid cancer, demonstrated that IL-10 helps to maintain CD8+ T cell-mediated tumor control and improves patients’ responses to PD-1 blockade." (PMID 33526861, 2021). "Indeed, cancer cell-derived cytokines, like TGFβ and IL-10, frequently direct differentiating tumor-infiltrating immune cells toward a tumor-promoting phenotype." (PMID 34207286, 2021). "However, recent studies also suggest that IL-10 provides significant anti-tumor effects in several mouse models." (PMID 34769278, 2021).
tumor (continued). "Most importantly, our results suggest that an anti-inflammatory (IL-10) cytokine and Th2-polarized immune balance in the tumor microenvironment may inhibit PC-3 cell growth." (PMID 34563040, 2021). "And IL-10 could also enhance NK lysis of tumor cells through downregulating the expression of inhibitory ligand, major histocompatibility complex class I molecule (MHCI), on tumor cells." (PMID 33717103, 2021). "In addition, treatment with recombinant IL-10 enhances nivolumab-induced anti-tumor activities in a small portion of these patients." (PMID 34769278, 2021). "Additionally, along with NK cells and Th17 cells, Th22 cells secrete IL-22, which has a similar structure to IL-10, which promotes tumour progression." (PMID 34298779, 2021). "PMNs also accumulate in tumor stroma when IL-10 is present in the TME." (PMID 35003081, 2021). "Tumor cells produce IL-10 and can therefore evade the immune system." (PMID 33578830, 2021). "However, a combination of IL-10 and 14G2A had a similar effect on tumor volume and mice survival as did 14G2A administration alone." (PMID 33912464, 2021). "sh‐c‐Myb or PD‐L1 alone into FLO‐1 cells increased Fas, IFN‐γ, and IL‐2 expression, but decreased FasL, IL‐4, and IL‐10 expression in the tumor tissues, and cotransfection of sh‐c‐Myb and PD‐L1 showed more significant trends compared with transfection of sh‐c‐Myb or PD‐L1 alone." (PMID 34586738, 2021). "Specifically, TAMs, myeloid-derived suppressor cells and dendritic cells have been shown to play a crucial role in tumor immune evasion by secreting IL-10, IL-12 and arginase-1, leading to suppression of CD8+ T-cell activity and reduced activity of effector T cells." (PMID 34717714, 2021). "Hence, the resolution of this contradiction of pro vs. anti-tumorigenic role of Th17 cells in CxCa would perhaps require further subtyping of tumor-infiltrating Th17 cells into those producing IFN-γ vs. IL-10 (Guéry and Hugues, 2015)." (PMID 33996630, 2021). "IL-4 induces immune deviation from TH1 to TH2 responses, which prevents tumor rejection; IL-10 suppresses the anti-tumor immunity and contributes to tumor immune escape and IL-13 compromises the anti-tumor response by inhibiting IFN-γ secretion and CD8+ T lymphocyte activity." (PMID 35047997, 2021). "Therefore, successful treatment requires more specific identification of tumor immune signatures when targeting IL-10 and TGF-β." (PMID 34336860, 2021). "In tumor tissue, mainly pro-tumorigenic, M2-like M-MDSCs are the dominant type, which inhibit tumor cell killing mediated by cytotoxic T lymphocytes primarily through IL-10, TGF-β, and ARG1." (PMID 33918295, 2021). "Summarizing the literature data, the following scheme might be assumed for the effects of IL-10 and IL-17 on the tumor process." (PMID 34443443, 2021). "Chemoresistant glioma (GLTMZ) promotes M2-like polarization (CD11b+Gr1+CD68+CD206+) characterized by a significant increase in the release of immunosuppressive interleukin (IL)-10, which sustains tumor proliferation, CD206 expression, and arginase activity (proposed M2-like marker)." (PMID 34646780, 2021). "Then, we measured IL-6 and IL-10, which were involved in immune response in tumor cells." (PMID 33959183, 2021). "Recent studies suggest that IL-10 might also exert some intrinsic anti-tumor T cell responses, and clinical studies using recombinant IL-10 alone or in combination with ICI are underway." (PMID 34769278, 2021). "This would explain the reduction on IL-10 amounts within the tumor tissue." (PMID 34282787, 2021). "However, in the context of CD4+T or NK cells deletion, the LLC or B16F10 tumor-bearing mice processed by IL-10 or Ad-hTERT presented shrinking tumor and improved survival compared with PBS control group." (PMID 33717103, 2021).